THPO (thrombopoietin)
Diseases named in the same sentence as THPO in open-access papers (continued):
Sharing a sentence is not in itself a finding about the gene and the disease.
cancer (34 papers, 2013 to 2026). A tumor composed of atypical neoplastic, often pleomorphic cells that invade other tissues. "GSEA has revealed that THPO is involved in activating several key signaling pathways implicated in cancer pathophysiology, notably the Notch and TGF-β pathways, as well as pathways related to interferon responses." (PMID 41049174, 2025). "A third example of pseudointron possibly implicated in cancer pathogenesis is found within the Thrombopoietin (THPO) gene." (PMID 24204383, 2013). "Earlier studies have identified that cancer cells can induce circulating thrombopoietin production; furthermore, higher thrombopoietin level is associated with gastrointestinal cancers, and a possible relationship between more advanced clinical stages and thrombopoietin has been also suggested." (PMID 35071777, 2022). "Cancer cells produce IL-6 and thrombopoietin to exploit protumor impact and induce paraneoplastic thrombocytosis." (PMID 38745688, 2024). "The presence of malignant tumors can incite an escalation in platelet (PLT) counts through the release of thrombopoietin (TPO) and interleukin-6 (IL-6)." (PMID 38439014, 2024). "Thrombopoietin is likely to be 1 of multiple factors that can impact platelet number, production, and consumption in dogs with carcinoma." (PMID 34881459, 2022). "Thrombopoietin concentrations (median [range]) were significantly higher in dogs with carcinoma when compared to controls (87.42 pg/mL [0 to >600] vs 15.99 pg/mL [0 to >600], P < .001)." (PMID 34881459, 2022). "The liver is the major organ producing thrombopoietin, which is a niche component that is critical for cancer cell colonization." (PMID 36046433, 2021). "Reactive thrombocytosis is induced by chronic inflammation, cancers, or infectious diseases, by accelerating the production of thrombopoietin and cytokines." (PMID 32858869, 2020). "Ferrous sulfate, folic acid, erythropoiesis-stimulating agents, thrombopoietin, and colony stimulating factors are among many common hematological stimulating agents that have been studied to possibly address these AEs in various cancers." (PMID 37835597, 2023). "Moreover, the release of pro-inflammatory cytokines by cancer cells resulted in the upregulation of thrombopoietin in the liver thereby inducing megakaryopoiesis and increasing platelet count." (PMID 35158817, 2022). "The process of thrombopoietin signaling and cancer immunoediting might rely upon a variety of cytokines such as interferon gamma and cell types such as NK cell, which could be affected by JAK inhibition." (PMID 35087406, 2021). "Thrombopoietin-mediated activation of lysine degradation reduces oxidative stress via the Lys-Glu pathway and induces c-myc to recruit chromatin modifiers to regulate gene expression in cancer cells." (PMID 36046433, 2021). "Thrombopoietin is the main regulator of platelet concentration in the blood, and it would be of interest to examine whether thrombopoietin levels are high in patients with high platelet counts and cancer at other sites." (PMID 34383058, 2021). "Prior studies have established that paraneoplastic thrombocytosis is driven in part by cancer cell-mediated release of interleukin-6 (IL-6), which stimulates the production of hepatic-derived and/or cancer-cell derived thrombopoietin to drive platelet overproduction." (PMID 33142915, 2020). "However, the presence of thrombopioetin detected by immunohistochemistry is attributed to the capture of thrombopoietin due to thrombopoietin receptor expression in human cancer cells." (PMID 28465688, 2017). "The study of THPO in the context of cancer provides a compelling example of how molecules known for their roles in normal physiological processes may have critical implications in tumorigenesis and cancer progression." (PMID 41049174, 2025).
cancer (continued). "TNS2 inhibits AKT/PKB signaling via C1-TEN (C1 domain-containing phosphatase and TENsin homologue) and mediates TPO (Thrombopoietin)/c-Mpl pathway, which engages AKT signaling in induction of cancer growth." (PMID 27285760, 2016). "Thrombopoietin was increased in dogs with carcinoma regardless of platelet count, and the majority of dogs with carcinoma had platelet counts within the reference interval." (PMID 34881459, 2022). "Thrombopoietin concentrations were significantly higher in dogs with carcinoma, regardless of platelet count." (PMID 34881459, 2022).
infection (17 papers, 2012 to 2025). The state of being infected such as from the introduction of a foreign agent such as serum, vaccine, antigenic substance or organism. "A wide range of cytokines, such as IL-3, IL-11, and granulocyte–macrophage colony-stimulating factors, as well as thrombopoietin and IL-6, are involved in stimulating platelet production in response to infection." (PMID 40427060, 2025). "Following the increased release of thrombopoietin and lots of inflammatory factors in serious infection, the platelet activation will be elevated and more large platelets will be released into the circulation." (PMID 32587473, 2020). "Acute IFN-γ exposure has been shown to induce both myelopoiesis and granulopoiesis in response to an infection, but chronic IFN-γ exposure has been shown to cause HSPC arrest through the binding and occlusion of the HSPC pro-survival factor thrombopoietin (TPO) to its cognate receptor c-MPL." (PMID 33193358, 2020). "Additionally, sagA complemented GAS induces a 2-fold or greater loss in MCP-1, MCSF, MDC, MIP-1b, Thrombopoietin, and TIMP-2 compared to the SLS-deficient mutant infection." (PMID 30018884, 2018). "In severe infection, the increased release of thrombopoietin and numerous inflammatory cytokines (e.g., interleukin-1, -3 and -6 and tumor necrosis factor-α) result in increased thrombopoiesis and an enhanced expression of younger large platelets into the bloodstream." (PMID 30533065, 2018). "In severe infection, increased release of thrombopoietin and various inflammatory cytokines, such as interleukin-1, −3 and −6 and tumor necrosis factor-α, result in increased thrombopoiesis and enhanced expression of younger large platelets into the blood circulation." (PMID 29084523, 2017). "Some studies suggested that system or local infection could increase release of thrombopoietin and different inflammatory cytokines, such as IL-1, IL3 and IL6 and tumor necrosis factor-α, result in increasing thrombopoiesis and lead to the production of younger large platelets in blood circulation." (PMID 35614411, 2022). "Cytokines GM-CSF, GRO-α, I-309, IL-1β, IL-6, MCP-1, MCP-2, TNF-α, thrombopoietin, BLC, Flt-3 ligand, HGF, IP-10, MIF, and MIP-3α were elevated by ≥1.5 fold relative to mock infection in both independent biological replicates of the cytokine array." (PMID 31536604, 2019). "After continuous treatmentof granulocyte colony-stimulating factor and thrombopoietin, neutropaeniapersisted for 3 weeks and patient recovered without any signs of infection." (PMID 29755117, 2018).
bacterial infections (1 paper, 2025). "It should be noted that the levels of PLT may be affected by platelet-stimulating drugs such as thrombopoietin (TPO) and platelet transfusions, and secondary bacterial infections can increase WBC levels." (PMID 39998055, 2025).
cardiovascular diseases (1 paper, 2023). "Dysregulation of THPO has been implicated in cardiovascular diseases, which are prevalent in 45,X and 47,XXY." (PMID 36978128, 2023).
immune disorders (1 paper, 2022). "In particular, the SH2B3 locus on chromosome 12 stands out in this regard, with GWAS signals for seven immune disorders colocalizing with three trans-regulated proteins (THPO, ICAM2, CXCL11), all involved in positive regulation of immune system processes (GO:0002684)." (PMID 35078996, 2022).
kidney disease (1 paper, 2024). "In a mouse model of antibody-mediated chronic kidney disease (AMCKD), renal-derived thrombopoietin (TPO) boosts the production of myeloid cells and platelets, aggravating chronic thromobinflammation in the microvasculature, and TPO neutralization can ameliorate this kidney disease." (PMID 38449859, 2024).
THPO also shares sentences with these, for which no sentence is quoted: idiopathic thrombocytopenic purpura (6 papers); congenital amegakaryocytic thrombocytopenia (4); alcohol abuse (3); fibrosis (3); liver failure (3); viral infection (3); bronchopulmonary dysplasia (2); chronic hepatitis C (2); Coagulopathy (2); erythrocytosis (2); Hydrocephalus (2); lymphoma (2); Myelodysplasia (2); Neonatal sepsis (2); Pancytopenia (2); SARS-CoV infection (2); severe aplastic anemia (2); thrombosis (2); acute myocardial infarction (1); acute respiratory distress syndrome (1); anorexia nervosa (1); antiphospholipid antibody syndrome (1); Autoimmunity (1); cardiomyopathy (1); cerebral infarction (1); Coronary Artery Disease (1); Disseminated intravascular coagulation (1); dysfibrinogenemia (1); Endotoxemia (1); esophageal cancer (1).
A further 39 diseases each share a sentence with THPO in 1 paper.